LY96 (lymphocyte antigen 96)
Diseases named in the same sentence as LY96 in open-access papers (continued):
Sharing a sentence is not in itself a finding about the gene and the disease.
tumor (39 papers, 1989 to 2026). "Then, LPS binding to LY96 causes disruption of the blood–brain barrier, triggering chronic and insidious inflammation formation in the brain, promoting glial cell carcinogenesis and exacerbating tumor growth." (PMID 38472293, 2024). "LY96 may also regulate classic tumor-associated pathways in several cancers and is related to drug resistance." (PMID 35647025, 2022). "Moreover, elevated LY96 expression in the tumor microenvironment has been linked to the recruitment of immunosuppressive populations, including myeloid-derived suppressor cells (MDSCs) and M2 macrophages, thereby suppressing cytotoxic T-cell function and exacerbating tumor progression." (PMID 41150760, 2025). "Through external validation using GSE268238, we confirmed that LY96 was highly expressed in macrophages from tumor tissues." (PMID 40620715, 2025). "We found that LY96 was differently expressed between tumor and normal tissues and was significantly upregulated in most types of cancers." (PMID 35647025, 2022). "LY96 was positively correlated with immune, stromal, and estimate scores and was negatively correlated with tumor purity across 33 cancers using the ESTIMATE algorithm." (PMID 35647025, 2022). "We also analyzed the LY96 expression in different tumor cell lines in the CCLE database, and the results revealed that LY96 was highly expressed in SKCM, LGG, GBM, and CLL, and was low expressed in NB, COAD/READ, STAD, and UCEC cells." (PMID 35647025, 2022). "We also investigated the correlation between LY96 and copy number, DNA methylation, somatic mutation, MSI, TMB, tumor microenvironment (TME), and immune cell infiltration in various types of cancers." (PMID 35647025, 2022). "More relevant to time of day, some inflammatory mediators (Myd88, Cd4, Tlr9, Cd38, C3, Ly96) demonstrated nyctohemeral (day versus night) differences in control brain tissues that were abolished in tumor-bearing and/or tumor-resected mice." (PMID 31019214, 2019). "Finally, we confirmed the high expression of LY96 in tumor tissue macrophages using immunofluorescence." (PMID 40620715, 2025). "Our analysis demonstrated that LY96 was positively correlated with tumor-promoting immune cells, including M1 macrophages and T cell regulatory Tregs, whereas high LY96 expression was negatively correlated with tumor immune suppression cells, including activated CD4 memory T cells and CD8 T cells." (PMID 35647025, 2022). "In addition, compared with adjacent tissues, LY96 expression was significantly different in 22 types of tumor tissues." (PMID 35647025, 2022). "This article may help to elucidate the role of LY96 in tumor occurrence and progression, which may promote the development of immunotherapy and targeted therapy in cancers." (PMID 35647025, 2022). "LY96 encodes MD2, an accessory molecule required for the activation of toll-like receptor-4, which promotes cell survival and induces the secretion of immunosuppressive molecules that promote tumor evasion from immune surveillance." (PMID 18030354, 2007). "LY96 is related to DNA methylation, copy number, microsatellite instability (MSI), somatic mutation, tumor mutation burden (TMB), tumor microenvironment (TME) features and immune cell infiltration in cancers, and LY96 can contribute to drug resistance and regulate classic tumor-associated pathways." (PMID 36998605, 2023). "Similar to before, LY96 positive macrophages secrete TNF and TGFB1 that act on tumor cells, thereby enhancing tumor cell proliferation." (PMID 40620715, 2025). "Data from TCGA were used to explore the expression differences of NPC2, LY96, and TPP1 at the overall tumor level." (PMID 40620715, 2025). "Cell communication analysis revealed increased interaction in tumor tissues, especially involving NPC2, LY96, and TPP1 positive macrophages, which facilitated tumorigenesis and immune evasion." (PMID 40620715, 2025).
tumor (continued). "Like NPC2, LY96 positive macrophages secrete MIF affecting T cells, inhibiting T cell activity, and mediating tumor immune escape." (PMID 40620715, 2025). "We identified 51 upregulated genes in the tumor samples derived from the patients with relapse within 60 months, participating primarily in inflammation and innate immune responses (e.g., LYN, LY96, ANXA1)." (PMID 38256136, 2024). "LY96, markedly expressed in gastric cancer cells, can activate macrophage-mediated NF-κB and STAT3 pathways, thereby promoting tumor progression." (PMID 35647025, 2022). "Among 33 types of tumor tissues, high LY96 expression was found in KICH, PRAD, COAD, and READ, and low expression of LY96 was found in LUAD, MESO, SARC, and DLBC tissues." (PMID 35647025, 2022). "Afterwards the BDNF and LY96 mRNA levels were determined in the same tumor tissue samples and compared to the SFRP1 expression level in the particular tumor sample." (PMID 25036590, 2014). "Indeed, the categorization of macrophages according to NPC2, LY96, and TPP1 expression highlighted their differential impact on the tumor microenvironment." (PMID 40620715, 2025). "NPC2, LY96, and TPP1, highly expressed in TAMs, were implicated in promoting tumor growth and immune escape, offering potential targets for novel therapeutic interventions." (PMID 40620715, 2025). "Ultimately, we found that NPC2, LY96, and TPP1 are highly expressed in tumor tissues." (PMID 40620715, 2025). "Whereas AL139147.1 showed a novel positive correlation with ENTPD1 (CD39) and IL1R1, which are involved in tumor immune cells infiltration and tumor microenvironment alteration; AC131391.1 correlated with LY96, which plays a vital role in tumorigenesis by modulating host immunity." (PMID 36313374, 2022). "Lymphocyte antigen 96 (LY96 or MD2), which is from the toll-like receptor 4 (TLR4) signaling pathway, promotes the development of immunotherapy and targeted therapy of malignancies in tumor occurrence and progression." (PMID 36429083, 2022). "In stark contrast, this pattern was absent (Myd88, Cd4, Tlr9, Ly96) in tumor-bearing and/or –resected mice or reversed, in one case (C3)." (PMID 31019214, 2019).
cancer (31 papers, 2010 to 2025). A tumor composed of atypical neoplastic, often pleomorphic cells that invade other tissues. "Our results indicated LY96 expression was highly correlated with the somatic mutation profile in different types of cancers." (PMID 35647025, 2022). "For PFS, biomarkers were detected in 10 cancer types, with CALR, CASP8, FOXP3, and LY96 consistently identified in at least three cancers." (PMID 41150760, 2025). "LY96 emerged as a recurrent biomarker in four cancers (KICH, KIRC, LIHC, and STAD), and IFNB1 was identified in DLBC, KIRP, and STAD." (PMID 41150760, 2025). "Using LASSO, SVM-RFE, and RF algorithms, LY96 was identified as a prognostic biomarker in four cancer types for OS and in three cancer types for DFI and PFS." (PMID 41150760, 2025). "Four key genes CCL2, CCR7, LY96, and PTPRC, from ClusterK1 and five genes AURKA, CDK1, CCNA2, FEN1, and PLK1 from ClusterK2, were associated with at least one type of cancer." (PMID 38872418, 2024). "In contrast, IL6, CLAR, LY96, and NT5E, were determined to be significant risk factors for eight cancers." (PMID 38627900, 2024). "To further explore the biological processes related to LY96 in various cancers, we conducted GSVA and GSEA analyses using R software." (PMID 35647025, 2022). "Methylation was significantly negatively correlated with the transcription level of CD4 and LY96 in almost all the cancer types, contributing partially to the low expression of these genes." (PMID 36497433, 2022). "For DNA methylation, LY96 expression was negatively correlated with LY96 methylation in most cancers of 33 types of cancers, and the highest correlation occurred in UVM, ACC, MESO, SKCM, and KIRC." (PMID 35647025, 2022). "Our research reveals that the LY96 level is upregulated in most cancers, including STAD, COAD, LIHC, and BRCA, which showed higher expression changes relative to normal tissues." (PMID 35647025, 2022). "LY96 was also associated with copy number, DNA methylation, somatic mutation, MSI, TMB, TME characteristics, and immune cell infiltration in cancers." (PMID 35647025, 2022). "Our results indicated LY96 expression was highly correlated with DNA methylation in different types of cancers." (PMID 35647025, 2022). "The prognostic role of LY96 expression across cancers was analyzed using data downloaded from the TCGA database." (PMID 35647025, 2022). "LY96 is significantly upregulated and can be used as a prognostic factor in most types of cancers." (PMID 36998605, 2023). "Therefore, we analyzed the LY96 expression and its prognostic role in tumors by multiple databases, including Genotype Tissue-Expression (GTEx), Cancer Cell Line Encyclopedia (CCLE), TCGA, and cBioPortal." (PMID 35647025, 2022). "We also analyzed whether the LY96 expression was correlated with immune-related gene set across cancers, and the results indicated that LY96 was significantly related to these gene set in most types of cancers." (PMID 35647025, 2022). "This article may help to elucidate the role of LY96 in tumorigenesis, which may promote the development of immunotherapy and targeted therapy in cancers." (PMID 35647025, 2022). "LY96 was gradually upregulated from stages I to IV in several cancers." (PMID 35647025, 2022). "Moreover, we found LY96 may play a prognostic role in diverse cancers, and patients with high and low expression often show different clinical outcomes." (PMID 35647025, 2022). "Moreover, we found LY96 may play a prognostic role in most cancers, and patients with high or low LY96 expression often show different clinical outcomes." (PMID 35647025, 2022). "We analyzed the correlation between LY96 expression and various types of immune cells in the TIMER2 database and the results demonstrated that LY96 expression was significantly correlated with most types of immune infiltrated cells in most cancers." (PMID 35647025, 2022).
cancer (continued). "We analyzed the correlation between LY96 expression and immunotherapeutic relevant signatures, and the results indicated that LY96 was positively correlated with immune checkpoint, CD8 T effector, antigen processing machinery, EMT2, and PanF TBR’s pathway in most cancers." (PMID 35647025, 2022). "The role of LY96 in several specific tumors was well investigated; however, there is no pan-cancer analysis of LY96 in various types of cancers." (PMID 35647025, 2022). "Among 33 types of cancer, LY96 expression was positively correlated with copy number variation (CNV) in UVM, KIRC, LIHC, SKCM, and LUSC, whereas there was a negative correlation between LY96 expression and CNV in TGCT, UCEC, STAD, BLCA, COAD, and BRCA." (PMID 35647025, 2022).
bacterial infection (9 papers, 2014 to 2025). "LY96 (Lymphocyte antigen 96), also known as MD-2 (Myeloid Differentiation factor 2), is a molecular chaperone of TLR4 (Toll-like receptor 4); the TLR4/MD-2 complex was found to control the early immune responses against bacterial infection." (PMID 35767190, 2022).
LY96 also shares sentences with these, for which no sentence is quoted: colorectal cancer (9 papers); colitis (7); diabetes (7); Hepatic steatosis (7); Obesity (7); endotoxemia (6); osteoarthritis (6); asthma (5); inflammation (5); non-alcoholic fatty liver disease (5); glioma (4); Hypertension (4); inflammatory bowel disease (4); necrotizing enterocolitis (4); prostate carcinoma (4); systemic inflammatory response syndrome (4); type 1 diabetes (4); viral infection (4); Allergy (3); atrial fibrillation (3); cardiomyopathy (3); cardiovascular diseases (3); gastric cancer (3); heart failure (3); hyperlipidemia (3); leukemia (3); lung injury (3); lymph node metastasis (3); muscular dystrophy (3); acute kidney injury (2).
A further 120 diseases each share a sentence with LY96 in 2 papers or fewer.